OR6C4 (olfactory receptor family 6 subfamily C member 4)
Description:
Odorant receptor.
Synonyms: OR12-10
Tractability: Antibody: UniProt places it where antibodies can reach, with medium confidence; UniProt predicts a signal peptide or a membrane-spanning region; its Gene Ontology location is reachable by antibodies, with medium confidence.
Gene: Protein-coding gene on chromosome 12 (55,549,602 to 55,555,832, forward strand). Ensembl gene ENSG00000179626.
Subcellular location: Cell membrane
Pathways (Reactome):
Sensory Perception: Expression and translocation of olfactory receptors
Gene Ontology:
Molecular function: olfactory receptor activity; G protein-coupled receptor activity
Biological process: detection of chemical stimulus involved in sensory perception of smell; G protein-coupled receptor signaling pathway
Cellular component: plasma membrane; membrane
Genetic constraint (gnomAD): Loss-of-function variants: 20 observed, 15.91 expected, observed/expected ratio (o/e) 1.26, 90% interval 0.88 to 1.78. The synonymous counts are far from expectation, so gnomAD's model fits this gene poorly and the ratio says little. Missense variants: 486 observed, 382.44 expected, observed/expected ratio (o/e) 1.27, 90% interval 1.18 to 1.37. Synonymous variants: 179 observed, 140.35 expected, observed/expected ratio (o/e) 1.28, 90% interval 1.13 to 1.44.
Homologues: Orthologues: macaque OR6C4 (97% identical), rabbit OR6C4 (94% identical), guinea pig OR6C4 (92% identical), dog OR6C4B (86% identical). Paralogues in human: OR2AP1 (80% identical), OR6C76 (69% identical), OR6C74 (68% identical), OR6C75 (68% identical), OR6C3 (67% identical), OR6C65 (65% identical), OR6C1 (65% identical), OR6C2 (65% identical), OR6C70 (65% identical), OR6C6 (63% identical), OR6C68 (62% identical), OR6J1 (50% identical), and 6 more.